ESR1 (estrogen receptor 1)
Diseases named in the same sentence as ESR1 in open-access papers (continued):
Sharing a sentence is not in itself a finding about the gene and the disease.
polycystic ovary syndrome (29 papers, 2013 to 2025). A disorder that manifests as multiple cysts on the ovaries. "A germline mutation in the ESR1 gene, which encodes ER alpha, resulted in deep estrogen resistance, delayed puberty, and polycystic ovaries in a young girl." (PMID 41514592, 2025). "Polymorphisms in ESR1 and ESR2 have been consistently linked to susceptibility to polycystic ovary syndrome (PCOS) across various populations." (PMID 41153361, 2025). "Numerous studies have shown a positive correlation of ESR1 and ESR2 gene polymorphisms with polycystic ovary syndrome (PCOS) in Caucasian women and in the Chinese, Iranian, Pakistani, Greek and Brazilian populations." (PMID 36385124, 2022). "The protein is up-regulated in theca cells of polycystic ovaries, such that the ratio of ESR1 to ESR2 expression is elevated in PCOS, which may contribute to abnormal follicular development." (PMID 30214429, 2018). "Additionally, all ESR1-mutated women presented with bilateral multicystic ovaries and the absence of breast development." (PMID 36401248, 2022). "In polycystic ovarian syndrome (PCOS), where epigenomic instability affects Fshr, Cyp19a1, Esr1, and Igf1, PFASs intensify transcriptional repression through DNMT3A-mediated CpG hypermethylation and global hypoacetylation of H3K9 and H4K16." (PMID 40724853, 2025). "PCOS: polycystic ovary syndrome; FSHR: follicle-stimulating hormone receptor; ESR1: estrogen receptor 1; IVF: in vitro fertilization; rhFSH: recombinant human follicle-stimulating hormone; MII: metaphase II; MI: metaphase I; GV: germinal vesicle." (PMID 37012960, 2023). "Despite this, hyperandrogenism, LH hypersecretion, polycystic ovaries, and a lack of corpora lutea are features found in LET-induced PCOS models and even in ER-α (ESR-1) knockout mice." (PMID 37681921, 2023).
adenomyosis (28 papers, 2009 to 2025). The growth of endometrial tissue inside the muscular wall of the uterine corpus. "To summarize, there was a group of SMCs with high expression of transcription factor ESR1 around the invaginating site and lesions of adenomyosis." (PMID 40190183, 2025). "In adenomyosis, decreased expression of ESR1 and increased expression of ESR2 can be observed, attributable to the methylation-mediated suppression of ESR2 in normal endometrial tissue." (PMID 41278208, 2025). "ESR1 was highly expressed in the myometrium surrounding the invaginating site and lesions, indicating that ESR1 expressed in myometrium might be the spatially specific regulatory molecule of adenomyosis." (PMID 40190183, 2025). "Deconvolution of bulk RNA‐seq data of adenomyosis myometrium exhibited a higher proportion of ESR1+ SMC ecotypes within the AM group, further indicating the importance of ESR1+ SMC ecotypes." (PMID 40190183, 2025). "All estradiol receptor (ESR1, ESR2, GPER) expression levels were significantly higher in adenomyosis than in normal myometrium." (PMID 35956024, 2022). "The increased expression of ESR1 and ESR2 in PP adenomyosis lesions, although based on limited data, may indicate a heightened sensitivity to E2 in these tissues." (PMID 39935764, 2025).
Stroke (28 papers, 2010 to 2025). Sudden impairment of blood flow to a part of the brain due to occlusion or rupture of an artery to the brain. "Studies have shown an association between ESR1, or oestrogen receptor 1, and stroke, with a significantly increased risk of stroke in subjects with the ESR1 c.454-397CC genotype." (PMID 40137146, 2025). "Through network pharmacology and computational simulations, key targets associated with musk volatile compounds and stroke, including SRC, EGFR, ESR1, PTGS2, and DRD2, were identified." (PMID 40137146, 2025). "Further bioinformatics and network pharmacology studies suggest that the interaction between ESR1 and PF shows promise in the development of new active compounds for stroke." (PMID 40732222, 2025). "Among them, paeoniflorin (PF) was identified as the core active compound, and its interaction with ESR1 was verified by molecular docking as the key interaction for the treatment of stroke." (PMID 40732222, 2025). "The molecular docking result further shows that the core molecular mechanism of these seven herbs for stroke treatment shall be the interaction of PF and ESR1." (PMID 40732222, 2025). "In addition, network pharmacological analyses identified 180 potential targets of the major volatile compounds of musk associated with stroke, and five key targets (SRC, EGFR, ESR1, PTGS2, and DRD2)." (PMID 40137146, 2025). "However, DRD2 and C5aR1 are absent or negligible in marmoset reactive astrocytes with only ESR1 & IL6ST significantly upregulated 1-week after stroke." (PMID 34824275, 2021). "There is still great research value for the four more meaningful stroke-related proteins (STAT3, MMP2, ESR1, TERT) in this study, and pointed out the direction for our further research." (PMID 36133785, 2022). "Studies have shown that ESR1 can downregulate the expression of CYP1A1 and 20-HETE after stroke." (PMID 40864781, 2025). "Therefore, SRC, EGFR, ESR1, PTGS2, and DRD2 are closely related to the occurrence and development of stroke, and the volatile compounds of musk may treat nerve damage caused by stroke by binding to these key target proteins." (PMID 40137146, 2025).
autoimmune disease (27 papers, 2008 to 2024). A disorder resulting from loss of function or tissue destruction of an organ or multiple organs, arising from humoral or cellular immune responses of the individual to their own tissue constituents. "However, the SIRT1-regulated signaling pathway of these hub genes (ESR1) in autoimmune diseases has not been reported." (PMID 38835801, 2024).
cardiac hypertrophy (27 papers, 2010 to 2024). "Overexpression of the ESR1 protein product ERα might be a protective factor in disease progression, prevent cardiac hypertrophy, reduce arrhythmias, improve vascular endothelial function, and modulate innate immune signalling in DCs and macrophages." (PMID 37005704, 2023). "On Module 9 of NFAT and Cardiac Hypertrophy, YCHT ingredient can inhibit ESR1 target and HQT ingredient has inverse action, while YGJ shows mixed function." (PMID 31824313, 2019).
endometrial adenocarcinoma (27 papers, 2009 to 2025). "DSCAM-AS1 levels were found to be considerably associated with ESR1 expression (rho = 0.40, p = 8.9 × 10−8) and with ERα target gene TFF1 (PS2) (rho = 0.41, p = 2.6 × 10−8) in endometrial adenocarcinoma tissues." (PMID 35885035, 2022).
Cognitive impairment (26 papers, 2008 to 2025). Abnormal cognition is characterized by deficits in thinking, reasoning, or remembering. "Certain polymorphisms in the oestrogen receptor alpha (ESR1) have been linked to a decreased grey matter volume in the cerebral and cerebellar cortex as well as an increased risk of cognitive impairment in older women." (PMID 40730494, 2025). "The X and P alleles of ESR1 have been associated with elevated risk for cognitive impairment in Alzheimer patients and older adults." (PMID 30544539, 2018). "ESR1 variation has indeed been associated with a host of other outcomes such as coronary heart disease, height, bone mineral density, multiple sclerosis, cognitive impairment, and age at menarche." (PMID 18990228, 2008). "Polymorphisms of the estrogen receptor ESR1 and ESR2 genes have been linked with cognitive deficits and affective disorders." (PMID 30544539, 2018). "Another study reported that two of the ESR1 SNPs (rs8179176, rs9340799) and two of the ESR2 SNPs (rs1256065, rs1256030) were associated with the likelihood of older women developing cognitive impairment." (PMID 30544539, 2018). "The SNPs in ESR1 and RYR3 are of specific interest as they have been extensively studied and found to be involved with immunologic processes and brain functions, which are previously reported to be associated with cognitive impairment and decline." (PMID 33154391, 2020). "Polymorphisms in estrogen receptor genes (ESR1 and ESR2) have been associated with risk of developing cognitive impairment and in turn may play a role in cognitive aging." (PMID 33154391, 2020). "For instance polymorphisms in the estrogen receptor alpha and beta genes (ESR1 and ESR2) have been associated with cognitive impairment in old women in two large longitudinal studies, but their potential intermediate neuronal correlates have not been investigated." (PMID 25538545, 2014).
endometrioid adenocarcinoma (26 papers, 2009 to 2026). An adenocarcinoma characterized by the presence of malignant glandular epithelial cells resembling endometrial cells. "Beyond 90% endometrioid carcinoma express moderate to high levels of the ERα (gene symbol ESR1)." (PMID 33324448, 2020).
leukemia (25 papers, 2011 to 2026). A malignant (clonal) hematologic disorder, involving hematopoietic stem cells and characterized by the presence of primitive or atypical myeloid or lymphoid cells in the bone marrow and the blood. "Nevertheless, studies with tamoxifen in ESR1-/- leukemia cells should be conducted to confirm this hypothesis." (PMID 32276421, 2020).
myocardial infarction (25 papers, 2006 to 2025). Gross necrosis of the myocardium, as a result of interruption of the blood supply to the area, as in coronary thrombosis. "Later on, ESR1 Pvull CC genotype was found to be associated with myocardial infarction in different studies in older (>60 years old) men, older southern Brazilian subjects and over 1,000 Chinese men." (PMID 25077953, 2014). "The Framingham Heart Study showed that a higher risk of myocardial infarction was common to males with ERα gene (ESR1) variant." (PMID 16608521, 2006). "Whether there is an association of myocardial infarction in women with the ESR1 variant and if there is a significant interaction with elevated estrogen exposure has yet to be determined." (PMID 16608521, 2006). "Further, a number of candidate gene studies have identified associations with increased risk of CAD or myocardial infarction (MI) in individuals with deleterious variants in the estrogen receptor 1 (ESR1 or ERα,) or 2 genes (ESR2 or ERβ) causing dysfunctional or null activity." (PMID 40182431, 2025). "After adjusting for covariates, the wild, although less common, ESR1 PvuII CC genotype was associated with an OR = 2.0 (1.32–3.2, p = 0.004) for major atherosclerotic CVD and an OR = 3.0 (1.7–5.2; p<0.001) for myocardial infarction, while having T allele (CT or TT genotypes) conferred CV protection." (PMID 25077953, 2014).
coronary artery disease (24 papers, 2007 to 2025). "Individuals with variations in ESR1 are more susceptible to cardiovascular complications, including ischemic heart disease and MI." (PMID 33430254, 2021). "Genetic variation in ESR1 gene has been associated with liver related traits, for example, type 2 diabetes, coronary artery disease (CAD)." (PMID 32457812, 2019). "A long genotype group of a common thymine-adenine (TA) dinucleotide repeat polymorphism in the regulatory region of ESR1 has been associated with coronary artery disease." (PMID 19804633, 2009). "The ESR1 genetic variant is related to the susceptibility of coronary heart disease." (PMID 38780500, 2024). "In a population-based prospective cohort study involving 6408 participants, 59.2% women, polymorphisms c.454-397T>C and c.454-351A>G were observed in the ESR1, with the possibility of four haplotype alleles and during a seven-year follow-up, 285 patients had MI and 440 had ischemic heart disease." (PMID 33430254, 2021). "Previous studies have suggested that polymorphism rs9340799, one of the widely identified polymorphisms of ESR1, may relate to ischemic heart disease." (PMID 27453734, 2016). "Moreover, the identification of ESR1 as a regulatory factor in human ICM in this study correlates with the association of specific polymorphisms in the ESR1 gene to coronary heart disease." (PMID 25884818, 2015).
uterine cancer (24 papers, 2006 to 2025). Primary or metastatic malignant neoplasm involving the uterine corpus and/or the cervix. "ERα, encoded by the gene of estrogen receptor 1 (ESR1), is one of the major tumorigenic drivers in BC and uterine cancer." (PMID 36212422, 2022). "On the other hand, treatment of ERα-expressing breast and uterine cancer cells with HDAC inhibitors leads to suppression of ESR1 expression." (PMID 34831189, 2021).
endometrial tumors (23 papers, 2008 to 2025). "ESR1 was upregulated in breast, ovarian, and endometrial tumors but downregulated in cervical tumors." (PMID 38582811, 2024). "Previously established associations between estrogen receptor (ESR1) and progesterone receptor (PGR) loss of expression and poor survival are confirmed by applying receptLoss to mRNA expression data from endometrial tumors in TCGA." (PMID 32894083, 2020). "We found that ESR1 expression predicted good histological differentiation and survival in endometrial tumors in patients." (PMID 30510261, 2018). "The very low rate of circulating ESR1 mutation at baseline in our study is in line with the histological identification of ESR1 mutation in only 1.8% of 1034 endometrial tumors without prior treatment." (PMID 37924026, 2023). "Estrogen receptor 1 (ESR1) is a ligand-induced steroid hormone receptor that mediates estrogen signaling and regulates transcriptionally driving growth, proliferation, and differentiation including cellular processes, in many breast and uterine It functions as an oncogene in endometrial tumors." (PMID 39849382, 2025).
metastatic carcinoma (23 papers, 2005 to 2025). A carcinoma which has spread from the original site of growth to another anatomic site. "Methylation of ESR1 has been implicated in the molecular mechanism of endocrinological tolerance in metastatic cancers, including metastatic breast cancer patients." (PMID 37155147, 2023). "While gain-of-function mutations in ESR1, the gene encoding ERα, are relatively rare in primary breast cancer, 11–55% of metastatic cancers have point mutations in the ligand-binding domain of ER, especially in amino acids Y537 and D538." (PMID 34638457, 2021). "Interestingly, the altered expression of ESR1 was associated with anti-cancer drug resistance, and non-coding events were identified in the regulatory hotspot of AP2A1 in various metastatic cancers." (PMID 38132440, 2023).
osteoarthritis (23 papers, 2012 to 2025). A noninflammatory degenerative joint disease occurring chiefly in older persons, characterized by degeneration of the articular cartilage, hypertrophy of bone at the margins and changes in the synovial membrane. "Genetic analyses have revealed associations between alterations in ESR1, the gene encoding ERα, and osteoarthritis." (PMID 36869045, 2023). "For the 8 gene loci ESR1 rs2234693, CYP19A1 rs700518, ADAM12 rs3740199, ACE I/D rs4340, VDRrs731236, TGF-β rs1982073, FAS rs1800682, ADAMTS5 rs226794, the cumulative sample sizes were deemed sufficient to conclude that they are not correlated with osteoarthritis." (PMID 39248710, 2024).
serous ovarian cancer (22 papers, 2011 to 2025). "The aim of our study was to evaluate the frequency and the clinical relevance of ESR1 mutations in high-grade serous ovarian cancer (HGSOC)." (PMID 35954453, 2022). "In the present study we evaluated the frequency and the clinical relevance of ESR1 mutations in high-grade serous ovarian cancer (HGSOC)." (PMID 35954453, 2022). "Correlation between ESR1/EERES score and survival was further validated with RNAseq data from low-grade serous ovarian cancer." (PMID 38582811, 2024). "CDK2-mediated phosphorylation of EZH2 at T416 activates EZH2 to silence target genes—ERα gene (ESR1), leading to in high-grade serous ovarian carcinoma (HGSOC) and TNBC." (PMID 37803297, 2023). "The present study investigated the impact of the expression of SLCO and related genes coding for ABC-transporters, PXR, ESR1/2, and HER-2 in serous ovarian cancer patients treated with debulking surgery and platinium- and taxane-based chemotherapy." (PMID 30131693, 2018).
Hyperglycemia (21 papers, 2014 to 2025). An increased concentration of glucose in the blood. "For instance, two Lachnospiraceae were increased in the fecal samples of ESR1 KO males, and gut colonization by this bacterial family is associated with increased body weight and hyperglycemia in germ-free ob/ob mice." (PMID 26971397, 2016). "In the combinations of antiestrogens + alpelisib, high grade adverse events, including hyperglycemia, rash, and diarrhea are common and mutations in PTEN and ESR1 were associated with disease progression and resistance to the combinations." (PMID 36869202, 2023).
liver disease (21 papers, 2010 to 2025). "Recent reports indicate that abnormal expression of estrogen receptor alpha (ESR1) may be a hallmark for the progression of liver disease and HBV carriers presenting variant ESR1 have an extremely aggressive clinical course." (PMID 22727021, 2012). "The abnormal ESR1 expressions in the liver have been implicated in stimulating hepatocyte injury and may act as liver disease inducers or promoters." (PMID 22727021, 2012). "Estrogen and variant ESR1 participates in the pathogenesis of HBV-related liver diseases." (PMID 22727021, 2012). "Therefore, variant ESR1 may be a hallmark for the progression of liver disease and HBV carriers presenting variant ESRa1 have an extremely aggressive clinical course." (PMID 22727021, 2012). "Abnormal expression of ESR1 has been associated with liver disease in HBV infection; specifically, ESR1 polymorphism is associated with HBV-induced liver failure." (PMID 31578247, 2019). "Estrogen inhibits the activity of Kupffer cells and reduces the production of ROS via estrogen receptor α (ERα/ESR1), exerting a protective effect on various liver diseases." (PMID 40661312, 2025). "Therefore, genetic, epigenetic, and non-genetic (e.g., tamoxifen or fulvestrant, ESR1 targeting drugs) factors that affect ESR1 function and/or expression may contribute significantly to the liver transcriptome, drug metabolism, and liver diseases." (PMID 33540646, 2021).
lymphoma (21 papers, 2007 to 2025). A malignant (clonal) proliferation of B- lymphocytes or T- lymphocytes which involves the lymph nodes, bone marrow and/or extranodal sites. "Of particular importance is the replication of a significant association with FL and the ESR1 rs3020314 SNP in a second independent study of lymphoma, which suggests that estrogen bioavailability may be relevant in the pathogenesis of lymphoma." (PMID 18636124, 2008). "Thus, large pooled gene-environment studies of ESR1 gene variants and measures of hormone levels or history of hormone use may be useful to further explore the role of hormones in the pathogenesis of lymphoma." (PMID 18636124, 2008). "Though human lymph nodes express both ESR1 and ESR2, the predominantly expressed nuclear estrogen receptor in normal lymphocytes and lymphomas is ESR2." (PMID 35804870, 2022).